FGFR2 (fibroblast growth factor receptor 2)
Diseases named in the same sentence as FGFR2 in open-access papers (continued):
Sharing a sentence is not in itself a finding about the gene and the disease.
tumor (618 papers, 2005 to 2026). "Within the tumor microenvironment, tumor-associated macrophages (TAMs) can influence tumor dynamics through changing FGFR2 different isoform's expression." (PMID 41584352, 2026). "FGFR-specific tyrosine kinase inhibitors (F-TKIs) provide clinical benefit in iCCA, but FGFR2 fusion proteins carrying mutations in key tumor-associated sites confer a growth advantage to tumor cells and increase resistance to selective TKIs." (PMID 41513616, 2026). "Clinical data, including age, gender, tumor size, radiographic features, histological subtype, and recurrence history, were examined for associations with FGFR2 alterations." (PMID 42074087, 2026). "Although elevated FGFR2 expression is linked to reduced tumor cell proliferation, the exact relationship between FGFR2 signaling and cell-cycle regulation is not yet fully understood." (PMID 41567627, 2025). "Earlier reports suggesting the presence of FGFR2 mutations in GISTs likely reflected misinterpretation of data extrapolated from other tumor types." (PMID 41150770, 2025). "Conventional tumor markers lack diagnostic accuracy; recent advancements in next-generation sequencing have identified actionable mutations, such as FGFR2 fusions and IDH1/2 mutations, enabling targeted therapies that improve survival." (PMID 40227772, 2025). "In FGFR2+ TMEs, we confirmed that the node in the network associated with tumor cells was generally distant from the CD8+ T-cell effector immune cell types and near CD11b+/CD15+ granulocytes and CD68+/CD163+ macrophages." (PMID 39969434, 2025). "A percentage of 24.2 had FGFR2 mutations, and these tumours were significantly associated with target lesion reduction (OR = 14, p = 0.02)." (PMID 40205008, 2025). "Tumor growth is aided by FGFR2 dysregulation, and activating mutations in FGFR2 are seen in a variety of cancer types." (PMID 40227591, 2025). "For instance, FGF5 derived from cancer-associated fibroblasts can activate FGFR2 on tumor cells, initiating downstream Keap1/Nrf2/HO-1 signaling and enhancing resistance to ferroptosis." (PMID 40867889, 2025). "Additional workup revealed recurrent ACC for which complementary tissue and circulating tumor DNA analysis were positive for FGFR-2 mutations." (PMID 39077220, 2024). "We believe that by inhibiting FGFR-2 signaling, futibatinib directly attacked the driver mutation behind tumor growth." (PMID 39077220, 2024). "In the context of cSCC, FGFR2 gene amplification and mutations can lead to its constitutive activation, promoting oncogenic pathways that contribute to skin carcinogenesis." (PMID 39063983, 2024). "FGFR2 fusion/rearrangement are associated with good clinical outcomes and an immune-activated tumor microenvironment in patients with ICC." (PMID 38986528, 2024). "Other key driver gene amplifications, specifically MET, EGFR and FGFR2, in circulating tumor DNA were associated with numerically lower ORR." (PMID 38745009, 2024). "FGFR2 is usually implicated in ER-negative breast cancer, although a low FGFR2 expression is associated with higher proliferation markers and a higher tumour grade." (PMID 39596875, 2024). "In a bed-to-bench approach, we investigate FGFR2 fusion proteins bearing critical tumor-relevant point mutations." (PMID 38346946, 2024). "A single tumor with activating FGFR2 p.Y375C mutation also demonstrated overexpression of the FGFR2 mRNA." (PMID 39596194, 2024). "In FIGHT-202, all patients with reductions in tumor size followed by PD (n = 8) had developed one or more mutation in the kinase domain of FGFR2 predicted to promote kinase activation or impair pemigatinib binding." (PMID 38838500, 2024).
tumor (continued). "The patient received prior treatment with gemcitabine, cisplatin and nab-paclitaxel and, at progression, FGFR2 p.C382R mutation was detected in the tumor tissue and blood sample by sequencing analysis." (PMID 38326380, 2024). "In a bedside-to-bench approach, we compared the effect of first- and second-generation FGFR-inhibiting drugs on tumor cells with patient-derived FGFR2 alterations, including resistance-mediating point mutations." (PMID 38346946, 2024). "Treatment options were discussed including standard chemotherapy with cyclophosphamide, doxorubicin, and cisplatin versus off-label therapy with futibatinib since the tumor harbored an FGFR-2 mutation." (PMID 39077220, 2024). "•Comparative RNA sequencing analysis of control, FGFR1 and FGFR2 knockdown cells revealed gene-regulatory networks relevant for tumor invasion that are specifically associated with FGFR1." (PMID 37579831, 2023). "In our study we saw significant growth inhibition in a PDX model with FGFR2 amplification and tumor regression in a model with FGFR2 amplification and FGFR2 Y375C mutation." (PMID 37980453, 2023). "A biopsy of post-progression tumors and autopsies showed significant tumor heterogeneity and different FGFR2-acquired mutations, which explained the resistance to Infigratinib." (PMID 38203635, 2023). "In vitro, altered levels of ESRP1 or ESRP2 caused a switch of FGFR2 splicing between FGFR2-IIIb and FGFR2-IIIc, resulting in changes in tumor cell growth and metastatic potential." (PMID 37090731, 2023). "New-generation inhibitors are in development, such as RLY-4008, a specific FGFR2 inhibitor, retaining anti-tumour activity against the main resistance mutations." (PMID 37760415, 2023). "Although FGFR2-positive IHC was associated with PCR amplification (p < 0.05), only FGFR2-positive IHC expression was associated with increased tumor depth (p < 0.001) and lower overall survival (OS) (p = 0.007)." (PMID 37893023, 2023). "It is planned to expand this approach, especially FGFR2 staining to a larger patient collective and involve other diagnostic tools such as the tumor molecular burden (TMB) or homologous recombination deficiency (HRD) estimation." (PMID 35246724, 2023). "Despite the low sample size in the analysis, clinically meaningful anti-tumor efficacy was reported in patients with FGFR2 mutations or amplifications." (PMID 37681152, 2023). "In vitro, altered ESRP1 or ESRP2 levels caused a switch of alternative splicing of FGFR2 between FGFR2-IIIb and FGFR2-IIIc, resulting in changes in tumor cell growth and metastatic potential." (PMID 37090731, 2023). "Tumour volume was also reduced in tumours derived from ADAM17‐deficient FGFR2‐mutant EC cells (MFE280A17−/−, MFE296A17−/−, AN3CAA17−/−), further corroborating that ADAM17 activity is critical for tumour growth in FGFR2‐mutant EC cells." (PMID 37165578, 2023). "Recently, a meta-analysis provided evidence that FGFR2 overexpression is associated with greater depth of tumor invasion, higher rates of lymph node metastasis, more advanced disease stage and worse outcome." (PMID 36260159, 2023). "FGFR2 encodes a receptor tyrosine kinase for fibroblast growth factors, which are frequently implicated in tumor growth." (PMID 35482141, 2022). "The study, conducted with serial analysis of cell-free circulating tumour DNA (cfDNA) from three patients, showed that acquired resistance to infigratinib is correlated with point mutations in the FGFR2 kinase domain during progression." (PMID 36497187, 2022). "FGFR2 mutations were also significantly more common in MSI-positive tumours than CTNNB1 mutations and appeared to have shorter disease-free survival." (PMID 35269800, 2022). "FGFR2 amplification and fusion structural variants have been considered to be relevant tumour drivers owing to the consequential receptor overexpression and constitutive dimerization mediated by oligomerization domains in the fusion partners." (PMID 35948633, 2022).
tumor (continued). "Here we apply transposon-based screening and tumour modelling in mice, and find that the truncation of exon 18 (E18) of Fgfr2 is a potent driver mutation." (PMID 35948633, 2022). "Together, these data establish that E18 truncation of Fgfr2 is a bona fide tumour-driver alteration and the loss of the C terminus is a key determinant of FGFR2 oncogenicity." (PMID 35948633, 2022). "Previous study demonstrated that FGFR2 overexpression, mainly due to FGFR2 gene amplification, is associated with poor pathological features, including deeper tumor invasion, more LN metastasis, advanced tumor stage, and worse survival in GC." (PMID 34551773, 2021). "These resistant tumours showed the acquisition of secondary mutations in FGFR2, overexpression of MET, increased drug efflux activity, and inactivation of negative regulators of RAS signalling." (PMID 33413533, 2021). "The overall mutation frequencies of FGFR2 were 2.8% (309/10,967) for all tumor samples and 2.4% (262/10,953) for all patients across the 32 cancer types." (PMID 33968743, 2021). "By examining the whole exome sequencing of this patient, it was observed that the tumor presented missense mutations in the fibroblast growth factor receptor 2 (FGFR2) and mammalian target of rapamycin (mTOR) genes." (PMID 34358097, 2021). "The total alteration frequency of FGFR2 across all tumor types was relative low (~0–20%), and mutation took up a major portion in most cancer types." (PMID 33968743, 2021). "After in silico investigation of these mutations and the identification of activated FGFR2-downstream targets in the tumor specimens, the MTB recommended treatment with an FGFR-inhibiting tyrosine kinase inhibitor." (PMID 34480077, 2021). "Droplet Digital PCR technology validated the ARID1A mutation and the FGFR2 amplification in bulk tumor DNA and in longitudinally collected ccfDNAs at three different time points of disease evolution." (PMID 34178989, 2021). "FGFR2 translocations, which are present in 5–38% of ICCs, represent driver mutations and predict tumor sensitivity to specific FGFR inhibitors in cholangiocarcinoma." (PMID 33692336, 2021). "Three advanced BTC patients (two had FGFR2 fusion and one with an FGFR2 mutation) exhibited stable disease with a 5–20% reduction in tumor size." (PMID 32748173, 2020). "Of these nine patients, three patients, two patients, and one patient were identified to have an IDH-1 mutation, FGFR-2 fusion, and FGFR-2 mutation in the tumour sample, respectively." (PMID 32899345, 2020). "Results of this study suggest that expression levels of FGFR2 in post-liver-resection tumor samples are closely related to tumor recurrence; specifically, increased expression of FGFR2 was associated with higher levels of recurrence." (PMID 31940413, 2020). "Deregulation of FGFR2 contributes to tumor progression and activating mutations in FGFR2 are found in several types of cancer." (PMID 31146385, 2019). "Targeted gene panel sequencing using the commercial Guardant360 assay revealed an FGFR2 V564F gatekeeper mutation in plasma circulating tumor DNA (ctDNA) of all three patients and several additional FGFR2 mutations in two of the patients." (PMID 31371345, 2019). "The loss of epithelial FGFR2 and changes in HS cofactors, are often found associated with tumor progression in a variety of tissues." (PMID 30761180, 2019). "We previously reported activating mutations of KRAS, as well as amplification of FGFR2, in a tumor that exhibited extreme resistance to photon radiotherapy." (PMID 31540114, 2019).
tumor (continued). "Overexpression of FGFR2 was reported to be oncogenic and associated with chemoresistant in tumor cells." (PMID 29987267, 2018). "Supporting these clinical findings, FGFR2 expression was associated with tumor cell proliferation, and also with cell cycle progression and anti-apoptosis." (PMID 26933914, 2016). "When the cases were stratified according to tumor features, it was observed that the SNPs in FGFR2 and TOX3 were associated with the disease." (PMID 26770289, 2016). "Our data now support the existence of CRC subgroups with decrease in ESRP expression but increase of mesenchymal splice variants in multiple FGFRs (at least FGFR2 and 3) important for tumor progression." (PMID 27650542, 2016). "Although these two statuses were significantly correlated (P < 0.05), only FGFR2 IHC expression was significantly associated with tumor depth (multivariate P < 0.001) and overall survival of patients (univariate P = 0.007)." (PMID 26933914, 2016). "Supporting these findings, FGFR2 overexpression was associated with tumor cell proliferation, cell cycle progression, and anti-apoptosis." (PMID 26933914, 2016). "The activity of regorafenib, M‐2, and M‐5 at PDGFRα and FGFR2, which are associated with maintenance of the tumor microenvironment 16, was also assessed in cell‐based assays." (PMID 27734608, 2016). "In contrast to FGFR2 IIIb, the IIIc variant expression correlated with distant metastasis and poor prognosis, and with aggressive behavior important for tumor progression in vitro and in vivo." (PMID 27650542, 2016). "FGFR2 amplification is associated with tumor cell proliferation, survival of GC cell lines, and indicates poor prognosis in patients with GC." (PMID 27014419, 2016). "In the present study, FGFR2 expression was strongly associated with the depth of invading tumor and with poor outcome." (PMID 26933914, 2016). "Cell lines were classified dependent on their ERα status, since this was the only tumour characteristic found to be associated with FGFR2 dependent risk, and their respective FGFR2 copy number." (PMID 24265722, 2013). "Since ER positivity constitutes the only significant tumour characteristic that was associated with the FGFR2 SNP haplotype, ERα expression levels in the MCF7 clones were determined." (PMID 24265722, 2013). "Somatic missense mutations of FGFR2 that are likely to be implicated in cancer development have also been demonstrated in primary tumors and cell lines of multiple tumor types." (PMID 23527311, 2013). "FGFR2 IIIb increases venous invasion but FGFR2 IIIc is associated with metastases, more aggressive tumours and confers PDAC cells features suggestive of cancer stem cells." (PMID 23125850, 2012). "The risk haplotype in FGFR2 is associated with both oestrogen receptor positive (ER+ve) and ER-ve tumours, although the association with ER+ve tumours is stronger." (PMID 21418638, 2011). "There was an association between presence of nuclear staining for FGFR2 in normal tissue and presence of nuclear staining in the adjacent tumour (Fishers exact test, p = 0.002)." (PMID 21418638, 2011). "Among the four different types of FGFRs, FGFR1 and FGFR2 have been specifically linked to tumour cells, and bFGF binds to FGFR1." (PMID 20606682, 2010). "Stratifying POSH cases by tumour characteristics identified SNPs in FGFR2 and TOX3 associated with ER-positive disease and SNPs in ATM associated with ER-negative disease." (PMID 19094228, 2008). "The differences in the associations between SNPs in FGFR2 and 8q24 and risk by ER and grade remained significant after permutation adjustment for multiple comparisons and after adjustment for other tumor characteristics." (PMID 18437204, 2008). "Liquid biopsies measuring FGFR2 amplification or splice variants via circulating tumor DNA (ctDNA) and cell-free RNA (cfRNA) may broaden sampling yet remain technically constrained in resolving isoform-level heterogeneity." (PMID 41584352, 2026).
tumor (continued). "Furthermore, the development of secondary mutations in the FGFR2 kinase domain has been identified as a major mechanism of tumor progression and treatment resistance in FGFR2 fusion-positive patients treated with targeted inhibitors." (PMID 41465387, 2025). "In the United States, the FDA approved ivosidenib for IDH1 mutations and pemigatinib, infigratinib, and futibatinib for FGFR2 fusions, alongside tumor-agnostic treatments for mismatch repair deficiency, NTRK fusions, ERBB2 amplifications, BRAF V600E mutations, and RET fusions." (PMID 39996880, 2025). "Provided that FGFR2 would indeed have a tumor-suppressive function, loss-of-function mutations of FGFR2 in ghM may help promote metastasis." (PMID 40724880, 2025). "This case presents a rare instance of a patient with recurrent ICC who, after undergoing radical surgery, exhibited tumor regression following a comprehensive treatment regimen predominantly featuring targeted therapy, prompted by the detection of an FGFR-2 mutation." (PMID 40255433, 2025). "Nevertheless, high FGFR2 expression assessed by these methods was reported to be associated with more aggressive clinical features including tumour depth, lymph node and distant metastases, and worse overall survival in patients with primary gastric and GEJ cancers." (PMID 38791079, 2024). "Furthermore, it has been shown that low levels of Tregs were associated to FGFR2 fusion/rearrangement, which is correlated to low grade and tumor cell differentiation." (PMID 39766138, 2024). "Splice switching from FGFR2 IIIb to FGFR2 IIIc is implicated in tumour progression." (PMID 39596875, 2024). "Also, FGFR2 is considered a GBM-associated tumor suppressor gene and high expression of FGFR2 in GBM is associated with increased patient survival." (PMID 37579831, 2023). "FGFR2 expression was associated with lower tumor grade and intestinal phenotype (p ≤ 0.0001)." (PMID 36260159, 2023). "This raises the possibility that several gain-of-function mutations in the FGFR2 gene could contribute to tumor growth and the formation of metastasis in EC by regulating ADAM17-mediated MAPK signaling pathways." (PMID 37759450, 2023). "It is worthy of note that the FGFR2 and TP 53 mutations correlated well with tumor grade progress." (PMID 35885641, 2022). "IDH1/2 mutations have been reported in 10–36% of iCCA tumours and FGFR2 fusions in 11–45%." (PMID 35484217, 2022). "FGFR2 expression was associated with a lower tumor grade and intestinal phenotype (p≤0.0001)." (PMID 35167603, 2022). "Interestingly, in a multifactorial analysis, MLH-1 followed the FGFR-2 mutation and led to higher tumour grade (p < 0.01)." (PMID 35885641, 2022). "Thus, human tumour models express and are dependent on E18-truncated FGFR2 and FGFR3 variants and are actionable by FGFR-targeted therapies." (PMID 35948633, 2022). "Thus, western blot analysis was used to study the molecular mechanisms underlying the anti-tumor effects of RK-019 and phosphorylation levels of FGFR2, and downstream proteins were determined and analyzed in SNU-16 and KATO III cells." (PMID 36210834, 2022). "The tumor gDNA target sequencing (DEPArray OncoSeek panel, Menarini Silicon Biosystems) confirmed the FGFR2 amplification and reported the same frameshift variant in APC, even though with a lower allele frequency (p.T1556Nfs∗3, AF: 14%), likely due to contamination by normal cells." (PMID 34178989, 2021). "Thus, upregulation of multisignaling triggered by FGFR2 activation collaborated with Brca1 deficiency creates an immunosuppressive environment that enhances tumor progression." (PMID 34514747, 2021).